BIRC3 (baculoviral IAP repeat containing 3)
Diseases named in the same sentence as BIRC3 in open-access papers (continued):
Sharing a sentence is not in itself a finding about the gene and the disease.
periodontitis (5 papers, 2017 to 2025). An acute or chronic inflammatory process that affects the tissues that surround and support the teeth. "Animal models of periodontitis and rheumatoid arthritis showed upregulated BIRC3 expression, which effectively attenuated inflammatory necrosis." (PMID 39428941, 2025). "Previous studies have reported elevated gene expression and protein levels of SOD2 and BIRC3 in patients with periodontitis compared to healthy individuals, suggesting their pivotal role in periodontal infection and inflammation." (PMID 39493178, 2024). "In our study, the upregulation of SOD2 and BIRC3 in human gingiva due to periodontal infection and thereby inflammation was confirmed using an animal model with experimental periodontitis and an in-vitro study on periodontal fibroblasts." (PMID 33435582, 2021). "SOD2 and BIRC3 expressions were also significantly increased in the gingiva from rats with experimental periodontitis, but the upregulation of both molecules was significantly diminished in the concomitant presence of orthodontic tooth movement." (PMID 33435582, 2021). "Our investigation revealed higher SOD2 and BIRC3 gene expression and protein levels in gingiva from periodontitis patients as compared to periodontally healthy gingiva, suggesting a critical role of these molecules in periodontal infection and inflammation." (PMID 33435582, 2021). "First, we analyzed the SOD2 and BIRC3 gene expressions in gingiva of periodontally healthy and periodontitis subjects." (PMID 33435582, 2021). "Interestingly, BIRC3 may also play a role in the association between periodontitis and atherosclerosis because BIRC3 was down-regulated in aortic tissues after oral polybacterial infection with P. gingivalis, Treponema denticola, Tannerella forsythia, and F. nucleatum in ApoE null mice." (PMID 33435582, 2021). "As evidenced by real-time PCR, the transcriptional levels of SOD2 and BIRC3 were significantly (p < 0.05) elevated at gingival sites of experimental periodontitis." (PMID 33435582, 2021). "The quantitative real-time PCR analysis revealed significantly (p < 0.05) increased SOD2 and BIRC3 levels in gingival biopsies of periodontitis patients as compared to gingival samples from periodontally healthy individuals." (PMID 33435582, 2021). "SOD2 and BIRC3 were also studied in gingiva from rats with experimental periodontitis and/or orthodontic tooth movement." (PMID 33435582, 2021). "Interestingly, the effect of F. nucleatum on the SOD2 and BIRC3 levels was similar to the actions of clinical periodontal infection, confirming the important etiological role of F. nucleatum in periodontitis." (PMID 33435582, 2021). "Gingiva from periodontitis patients showed significantly higher SOD2, BIRC3, CASP3, and CASP9 levels than periodontally healthy gingiva." (PMID 33435582, 2021). "SOD2, BIRC3, and the apoptotic markers caspases 3 (CASP3) and 9 (CASP9) were analyzed in gingiva from periodontally healthy and periodontitis subjects by real-time PCR and immunohistochemistry." (PMID 33435582, 2021). "Then, gingival biopsies from periodontally healthy and periodontitis subjects were also studied for the presence of SOD2 and BIRC3 by immunohistochemistry." (PMID 33435582, 2021). "Since SOD2 and BIRC3 can inhibit apoptosis, we additionally investigated the levels of the apoptotic markers CASP3 and CASP9 in gingival biopsies from periodontally healthy and periodontitis subjects." (PMID 33435582, 2021). "The aim of the study was to clarify whether orthodontic forces and periodontitis interact with respect to the anti-apoptotic molecules superoxide dismutase 2 (SOD2) and baculoviral IAP repeat-containing protein 3 (BIRC3)." (PMID 33435582, 2021). "The present in-vitro and in-vivo study was therefore designed to clarify whether orthodontic forces and periodontitis interact with respect to the regulation of the two anti-apoptotic molecules SOD2 and BIRC3." (PMID 33435582, 2021).
periodontitis (continued). "In contrast, the roles of GADD45B and BIRC3 have not been thoroughly investigated in the progression of periodontitis." (PMID 29190775, 2017). "However, when these sites were also affected by experimental orthodontic tooth movement, the periodontitis-induced upregulation of SOD2 and BIRC3 was significantly (p < 0.05) reduced again, demonstrating an inhibitory effect of orthodontic forces on these molecules in periodontal infection." (PMID 33435582, 2021).
rheumatoid arthritis (5 papers, 2017 to 2025). A chronic, systemic autoimmune disorder characterized by inflammation in the synovial membranes and articular surfaces. "The overactivation of Birc3 may be associated with chronic inflammatory diseases, such as rheumatoid arthritis and inflammatory bowel disease, as it can continuously activate the NF-kB signaling pathway, leading to sustained inflammation." (PMID 40243536, 2025). "Combining anti-tumor necrosis factor therapy with cIAP1/2 inhibitors by blocking the BIRC2/BIRC3-mediated apoptotic pathway has the potential to improve therapeutic efficacy and effectively reduce symptoms and disease progression in rheumatoid arthritis." (PMID 39301019, 2024). "Although BIRC3 inhibitors show promise in treating rheumatoid arthritis, potential side effects must be carefully considered, such as inducing apoptosis in normal cells dependent on BIRC3-regulated pathways and triggering adverse immune responses due to its role in immune regulation." (PMID 39301019, 2024).
Arthritis (4 papers, 2015 to 2025). Inflammation of a joint. "BIRC3 is a direct target of ATF6α, and model mice with ATF6α deficiency exhibit reduced arthritis progression, resulting in significant reductions in clinical and pro-inflammatory markers in the joints." (PMID 41291434, 2025).
atherosclerosis (4 papers, 2015 to 2022). A disease characterized by the build-up of fatty material and calcium deposition in the arterial wall resulting in partial or complete occlusion of the arterial lumen. "Periodontal microbiome infection is associated with significant decreases in Apoa1, Apob, Birc3, Fga, FgB genes that are associated with atherosclerosis." (PMID 26619277, 2015). "In rat atherosclerosis PCR array, Abca1, Bax, Bcl2, Bcl2a1, Cd44, Fabp3, Hbegf, Lypla1, Ptgs1, Selplg, Tgfb2, Tnc, and Vegfa had reverse trend between WT and MU groups, while the trends of Bcl2l1, Bid, Birc3, Cxcl1, Fas, Fn1, Itga2, Itga5, Lif, Nfkb1, Nr1h3, Ppard, and Sod1 were consistent." (PMID 34545275, 2021). "IL6, CXCL8, CCL2, SOD2, NFKBIA, and BIRC3 were identified as the top 6 hub genes in the magenta module (human cardiomyocyte samples) and were mainly enriched in the NOD-like receptor signaling pathway, IL-17 signaling pathway, TNF signaling pathway, lipid and atherosclerosis signaling pathway." (PMID 36426222, 2022).
autoimmune disease (4 papers, 2022 to 2024). A disorder resulting from loss of function or tissue destruction of an organ or multiple organs, arising from humoral or cellular immune responses of the individual to their own tissue constituents. "Although both apoptosis resistance and immune responses contribute to the development and progression of autoimmune diseases such as RA, relatively little is known about the regulation of BIRC3 at the interface of the two phenotypes in RA." (PMID 36300114, 2022). "Finally, a more robust comparative analysis is needed, especially comparing the role of BIRC3 in RA with other autoimmune diseases, to provide a broader perspective on its specific functions and potential as a therapeutic target." (PMID 39301019, 2024). "Consequently, the targeted modulation of BIRC3 gene expression and ubiquitination processes in TNFR1 or TRAIL signaling mediated by BIRC3 (cIAP2) present promising strategies for enhancing treatments for related disorders, including autoimmune diseases." (PMID 39301019, 2024). "Although CD is a heterogeneous autoimmune disease, the expression levels of five key genes (TNF, BIRC3, ANXA1, TNIP3, and FKBP11) were significantly higher in most CD tissues than that in normal tissues." (PMID 37047025, 2023).
breast tumor (4 papers, 2009 to 2017). "Furthermore, it was also shown that MCPIP1 functions as a potent tumor suppressor and induces apoptosis of breast tumor cells by selectively enhancing mRNA decay of antiapoptotic gene transcripts, including Bcl2L1, Bcl2A1, RelB, Birc3, and Bcl3." (PMID 28197812, 2017).
esophageal cancer (4 papers, 2021 to 2025). A primary or metastatic malignant neoplasm involving the esophagus. "cIAP1 and cIAP2-encoding genes (named BIRC2 and BIRC3) are very closely located on chromosome locus 11q22.2, a region found amplified (11q21 amplicon) in human medulloblastoma, hepatic, breast, pancreatic, cervical, lung, oral squamous cell and esophageal carcinoma." (PMID 35204822, 2022). "BIRC3, a member of the IAP family, has been implicated in several cancers, including esophageal cancer, head and neck cancer, and CRC." (PMID 40260225, 2025). "Several esophageal cancer cell lines also showed upregulated BIRC3 and activation of the Wnt and fibroblast growth factor signaling pathways." (PMID 39428941, 2025). "This study revealed that dysfunction of BIRC3 and GAG-4 might promote resistance to therapy in esophageal cancer cells." (PMID 34488754, 2021).
nasopharyngeal carcinoma (4 papers, 2010 to 2025). A carcinoma arising from the nasopharyngeal epithelium. "Conversely, reducing FOLR1 levels alters key apoptotic and MAPK pathway genes (BIRC3, caspases, FOS, DUSP1, PRKX, TNFRSF10A), sensitizing taxol-resistant nasopharyngeal carcinoma cells to chemotherapy." (PMID 41439026, 2025).
oral cancer (4 papers, 2011 to 2025). "We found the upregulation of IL6, Ki67, c-myc, Akt, and BIRC3 genes in the oral cancer dataset-GSE30784 as well as in the analyzed head and neck statistics available at Oncomine." (PMID 36845732, 2023). "Here, we validate the amplifications of 11q13.3 and 11q22.1-q22.2 in OSCC and evaluated the expression of BIRC2 and BIRC3 with respect to lymph node metastasis and poor survival in oral cancer patients." (PMID 29167558, 2017). "Moreover, circDOCK1, functioning as a competing endogenous RNA (ceRNA), modulates BIRC3 expression, prompting apoptosis in oral cancer." (PMID 39967686, 2025).
osteosarcoma (4 papers, 2010 to 2016). A usually aggressive malignant bone-forming mesenchymal neoplasm, predominantly affecting adolescents and young adults. "BIRC3 has also been shown to be up-regulated in some osteosarcomas." (PMID 24349465, 2013).
colitis (3 papers, 2017 to 2021). Inflammation of the colon. "We observed that several key regulators including Akt1 kinase and BIRC3 were present only in control samples but not in DSS-7 animals, implying lower abundance of their SUMOylated forms in colitis-associated epithelium." (PMID 28659381, 2017).
COVID-19 (3 papers, 2021 to 2023). A disease caused by infection with severe acute respiratory syndrome coronavirus 2. "This also showed that stimulation post-BCG vaccination increased expressions of BIRC3, CCL3, CCL3L1, CCL4, CSF2, IL1B, and LTA, which in contrast, decreased in severe COVID-19." (PMID 36225326, 2022).
Ewing sarcoma (3 papers, 2008 to 2011). A small round cell tumor that lacks morphologic, immunohistochemical, and electron microscopic evidence of neuroectodermal differentiation. "We also found downregulation of the anti-apoptotic BIRC-2 (cIAP1) and BIRC-3 (cIAP2) proteins in Ewing’s sarcoma SK-N-MC xenografts." (PMID 21822457, 2011).
HIV-1 infection (3 papers, 2010 to 2025). The type species of lentivirus and the etiologic agent of acquired immunodeficiency syndrome (AIDS). "In addition, a previous study implicated the BIRC2 and BIRC3 protein products cIAP1 and cIAP3, respectively, in protecting macrophages from Vpr-induced cell death during HIV-1 infection." (PMID 40901928, 2025). "HIV-1 infection was monitored by flow cytometry for HIV-1 core proteins and qRT-PCR for unspliced HIV-1 genomic transcripts, while NF-κB activation was measured by qRT-PCR for CXCL8 and BIRC3." (PMID 39269169, 2024). "HIV-1 infection upregulated CXCL8 and BIRC3 gene expression, while HIV-1 ∆Vpr did not." (PMID 39269169, 2024).
Hypertension (3 papers, 2017 to 2025). The presence of chronic increased pressure in the systemic arterial system. "BIRC3 under-expression was associated with the occurrence of hypertension in OSA patients." (PMID 28520763, 2017). "We speculate that BIRC3 may play a role in protecting from hypertension in OSA patients through inhibiting endothelial cell apoptosis and NF-κB signaling." (PMID 28520763, 2017). "Subgroup analyses revealed that AMOT P130 protein expression was increased in OSA patients with excessive daytime sleepiness, BIRC3 protein expression was decreased in OSA patients with hypertension, and LGALS3 protein expression was increased in OSA patients with chronic kidney disease." (PMID 28520763, 2017). "AMOT and GALIG may constitute an important determinant for the development of hypersomnia and kidney injury, respectively, while BIRC3 may play a protective role in the development of hypertension." (PMID 28520763, 2017). "Subgroup analysis showed that OSA patients with hypertension had significantly deceased BIRC3 protein expression levels as compared to those without hypertension (0.04±0.06 versus 0.21±0.33 pg/ml, adjusted p = 0.048)." (PMID 28520763, 2017). "The findings extend reports linking AMOT with EDS in OSA patients, and provide direct evidence that perturbation of BIRC3 and LGALS3 signaling may play an important role in the mediation of hypertension and CKD in OSA patients, respectively." (PMID 28520763, 2017). "Moreover, we verified AMOT, PLEKHH3, ADAR, BIRC3, and LGALS3 protein over-expressions in the treatment-naïve OSA patients, and discovered a correlation between AMOT/BIRC3/LGALS3 protein expression and the presence of EDS/hypertension/CKD, respectively." (PMID 28520763, 2017).
marginal zone lymphoma (3 papers, 2020 to 2023). A usually indolent mature B-cell lymphoma, arising from the marginal zone of lymphoid tissues. "The Baculoviral IAP Repeat Containing 3 (BIRC3) is associated with marginal zone B-cell lymphoma and was suggested as a novel NK cell immune checkpoint in cancer." (PMID 33301474, 2020).
thymic carcinoma (3 papers, 2013 to 2023). Thymic carcinoma (TC) is a type of thymic epithelial neoplasm characterized by a high malignant potential. "In a gene expression analysis by microarray, thymic carcinomas were found to upregulate two anti-apoptotic genes (BIRC3 and SCYA20), two pro-apoptotic genes (PMAIP1 and MYC), and downregulate the pro-apoptotic gene MTCH2 when compared to B3 thymomas." (PMID 38201593, 2023). "T1889 thymic carcinoma cell lines express BIRC-3, and its knock-down by siRNA induces apoptosis." (PMID 38201593, 2023). "We found differential expression of anti-apoptotic genes in B3 thymomas and TSCC and could induce apoptosis by BIRC3 blockade in the thymic carcinoma cell line, 1889c." (PMID 24427739, 2013).
endometriosis (2 papers, 2022 to 2025). The growth of functional endometrial tissue in anatomic sites outside the uterine body. "In humans, BIRC3 and BIRC5 are expressed in the endometrium, and aberrant expression of these IAPs is associated to endometriosis and endometrial cancer." (PMID 34530503, 2022). "Increased expression of BIRC2, BIRC3, BIRC4, and BIRC5 is associated with endometriosis, and tumor necrosis factor-α increases BIRC3 expression in endometrial stromal cells in vitro." (PMID 34530503, 2022). "Baculoviral IAP repeat containing 3 (BIRC3) has not been studied in the context of endometriosis." (PMID 40698088, 2025). "BIRC3, CEL, and LEFTY1 were significantly less expressed in the endometrium of women with endometriosis than without (logFC = −0.79, p = 0.0051; logFC = −0.52, p = 0.0051; logFC = −0.61, p = 0.0099, respectively)." (PMID 40698088, 2025).
invasive carcinoma (2 papers, 2009 to 2026). A carcinoma that is not confined to the epithelium, and has spread to the surrounding stroma. "The spatial colocalization of BIRC3 with tumor vasculature in invasive carcinoma tissue suggests a novel interaction." (PMID 41972735, 2026).
lymph node metastasis (2 papers, 2016 to 2017). "Using qRT-PCR and IHC, we demonstrated that the overexpression of BIRC2 (cIAP1) and BIRC3 (cIAP2), both located on 11q22.1-q22.2, was associated with lymph node metastasis in OSCC patients." (PMID 29167558, 2017). "Upregulation of both BIRC2 and BIRC3 was significantly associated with lymph node metastasis (p < 0.002 and p < 0.007, respectively)." (PMID 29167558, 2017).
mastitis (2 papers, 2020 to 2025). Inflammation of breast tissue during lactation or postpartum due to an obstructed duct or infection. "Transcriptome analysis have shown that BIRC2 and BIRC3 are upregulated in mammary glands infected with Staphylococcus aureus response, suggesting their role in immune response to mastitis." (PMID 41252605, 2025).
neuroblastoma (2 papers, 2017). Neuroblastoma (NB) is the most common solid, extracranial childhood tumor. "Under the condition that methylmercury decreased the viability of human neuroblastoma (IMR-32 cells) by 20%, methylmercury increased cleaved caspase-3 levels; on the other hand, mRNA level of BIRC3 was not changed by methylmercury treatment." (PMID 29229987, 2017).
preeclampsia (2 papers, 2021 to 2025). Preeclampsia is a hypertensive disorder of pregnancy that is characterized by new-onset hypertension with proteinuria presenting after 20 weeks of gestation, and depending on mild or severe forms may initially present with severe headache, visual disturbances, and hyperreflexia. "Overall, these results indicate that a decrease in CLDN1 inhibits BIRC3 expression and increases cleaved PARP levels thus participating in the pathogenesis of preeclampsia." (PMID 33784242, 2021). "In conclusion, we demonstrated that downregulation of CLDN1 regulates trophoblast apoptosis via a decrease in the levels of BIRC3 and downstream PARP, which is a new phenomenon in the pathogenesis of preeclampsia." (PMID 33784242, 2021).
thymoma (2 papers, 2013 to 2015). A neoplasm arising from the epithelial cells of the thymus. "By cluster analysis, different anti-apoptotic signatures were detected in type B3 thymoma and TSCC, including overexpression of BIRC3 in TSCCs." (PMID 24427739, 2013).
ZIKV infection (2 papers, 2017 to 2022). "In addition, the lack of a cytopathic effect could be due to the induction of the pro-survival genes during the ZIKV infection of hBMECs, including EGR1, ATF3, and BIRC3." (PMID 36557673, 2022).
Airway obstruction (1 paper, 2022). Obstruction of conducting airways of the lung. "Overall, induced sputum BIRC3 overexpression could predict heavier airway inflammation and airway obstruction." (PMID 35287655, 2022).
atopic dermatitis (1 paper, 2022). "Recently, researchers have identified a small subset of skin DCs called mregDCs with high expressions of BIRC3, LAMP3, IL15, CD40, and CCR7, and this subset has been thought to be associated with wound healing and the exacerbation of atopic dermatitis." (PMID 35280984, 2022).
basal cell carcinoma (1 paper, 2021). A carcinoma involving the basal cells.
cardiac hypertrophy (1 paper, 2022). "Also the following tachycardia-specific miR-1183-regulated targets showed a cardiovascular association: the gene NEU3 with cardiac fibrosis and CHD, ZNRD1 with CHD, TRIM16 with cardiac hypertrophy, BIRC3 with ischemic preconditioning, ARRDC3 with cardiac hypertrophy, and MTAP with ischemic stroke." (PMID 35805966, 2022).